STAT3 (signal transducer and activator of transcription 3)
Diseases named in the same sentence as STAT3 in open-access papers (continued):
Sharing a sentence is not in itself a finding about the gene and the disease.
cancer (continued). "The anaphylatoxins produced by the complement system have proven to play a pivotal role in inflammation and cancer progression, and its downstream effectors, like Interleukin 6, cause the constitutive activation of STAT3." (PMID 35800364, 2022). "Signal transducers and activators of transcription 3 (STAT3) were constitutively active in several cancer types, and such hyperactivity was associated with an adverse clinical outcome." (PMID 36517820, 2022). "The anti-cancer activity of cryptotanshinone has been found to be associated with the inhibition of STAT3 phosphorylation." (PMID 36105202, 2022). "IL-6 is an inducer of STAT3, and is a direct target of miRNA-26a and -26b, and STAT3 signaling is associated with cancer progression and metastasis." (PMID 36138741, 2022). "LCA was also found to activate Erk1/2 and in turn, suppress STAT3 phosphorylation to induce IL–8 expression that are implicated in cancer cell invasion and angiogenesis." (PMID 36497071, 2022). "Evidence for this stems from the detection of somatic mutations in PIK3CD, NFKB1, and STAT3 in human cancer genomes and the identification of their role in carcinogenesis." (PMID 35250968, 2022). "Currently, PKM2 is known as the cancer-specific PK isozyme, as its dimeric form has been associated with oncogenesis, acting as cancer-specific signaling molecules such as STAT3, histone H3, OCT-4 and HIF-1." (PMID 36077431, 2022). "Extensive studies have already demonstrated that inappropriate activation of specific STAT members contributes to oncogenesis, especially for the Janus kinase (JAK)/STAT3 pathway, which has been linked to many types of cancer." (PMID 36061181, 2022). "Since, in cancers, the NF‐кB pathway and activation of STAT3 are closely linked, we evaluated the activation of NF‐κB and the IKKα/β status in CRC cells treated with DCZ0415." (PMID 35194944, 2022). "Our results suggest that STAT3 inhibition is central in resistance exercise protective effects against cancer-induced muscle atrophy and strength loss." (PMID 35847939, 2022). "Growing evidence shows that targeting STAT3 and its associated pathways can be used to change the immunologic microenvironment of tumors in order to support cancer immunotherapies." (PMID 35606804, 2022). "Intriguingly, the PIM1 gene, encoding for the kinase PIM1, was one of the top upregulated genes in lung fibroblasts from aged mice, and its function was previously implicated in STAT3-mediated cell survival and cancer-associated fibroblast activation." (PMID 35167499, 2022). "STAT3 plays central roles in the development, maintenance, and progression of several human cancers, and STAT3 activation is associated with poor cancer prognosis, making this pathway an attractive drug target." (PMID 35562668, 2022). "Aberrant phosphorylation of STAT3 was reported in 70% of cancers and was associated with poor prognosis." (PMID 36230984, 2022). "Persistent activation of STAT3 induced by cytokines and growth factors is associated with cell proliferation, differentiation, and apoptosis in cancer." (PMID 35356799, 2022). "Stat3 and Tcf/Lef elements mediate cancer-associated FOSL1 induction in response to the IL6 and Wnt-beta-catenin pathways, respectively." (PMID 35326630, 2022). "Scientists reported its association with development of some cancers, where it acts through the STAT3 pathway." (PMID 36230984, 2022). "Runt-related transcription factor 2 (RUNX2) has a key role associated with the pathogenesis of some cancers and a downstream gene of the STAT3 pathway." (PMID 36547079, 2022). "The JAK2/STAT3 signaling pathway is involved in the progression of several cancers and is associated with other SOCS proteins through feedback regulation in various cell processes." (PMID 35126805, 2022). "The signaling pathways associated with miR-637 in cancer include the Jak/STAT3 signaling pathway, the Wnt/β-catenin signaling pathway, the ERK signaling pathway, and the PI3K/AKT signaling pathway." (PMID 36175921, 2022).
cancer (continued). "The mechanism underlying the Warburg effect and its association with cancer cell proliferation is not fully understood, but the STAT3 pathway is demonstrated to contribute to Warburg's vicious circle." (PMID 35356799, 2022). "Although other STAT factors, such as STAT1 and STAT5, have also been associated with cancers of the upper aerodigestive tract, we focused our current exploration on STAT3, based on our previous findings." (PMID 34850540, 2022). "The over‐expressions of PD‐L1 in cancer cells and PD‐1 in stromal cells were reported to be associated with the phosphorylation of STAT3, which demonstrated the immunosuppressive roles of the STAT3 pathway." (PMID 35356799, 2022). "Recent studies have emphasized the important role of transcription factor nuclear factor kappa B (NF-κB) and signal transducer and activator of transcription 3 (STAT3) in the progression of inflammation-associated cancer." (PMID 35733095, 2022). "We examined the expression of two well known STAT3 downstream target genes implicated in anti-apoptotic (Bcl-xL) and proliferative (Cyclin D1) cancer cell activities after treatment with mc-1Stat3 or dc-Stat3." (PMID 35847174, 2022). "ESCC cells can secrete IL-6 and other pro-inflammatory cytokines, including IL-8 and LIF, which have been implicated in cancer progression and immune evasion through the activation of STAT3 and YAP." (PMID 34063828, 2021). "Yet deviation of these processes is frequently observed in solid malignancies and is in part attributed to aberrant STAT3 activity in stromal cancer-associated fibroblasts." (PMID 34858425, 2021). "Several cytokines associated with cancer-induced wasting can stimulate muscle STAT3 phosphorylation." (PMID 34395422, 2021). "The JAK/STAT3 axis is a classic cell signaling pathway mediated by enzyme-linked receptors in cells and participates in the pathogenesis and development of cancers." (PMID 34867344, 2021). "Emerging evidence indicates that STAT3 is a key oncogene which is implicated in the activation of the signaling pathways involved in cell proliferation and cancer metastasis." (PMID 34876150, 2021). "Diverse signalling pathways are involved in carcinogenesis and one of such pathways implicated in many cancers is the interleukin 6/signal transducer and activator of transcription 3 (IL-6/STAT3) signalling pathway." (PMID 34078370, 2021). "It is reported that the transcription and translation levels of STAT3 in GC tissue are markedly higher than those in normal tissues adjacent to cancer, and p-STAT3 level was associated with the differentiation status of GC." (PMID 34224294, 2021). "We also focus on some key signaling pathways such as Wnt/β-catenin signaling, MAPK signaling, Hippo signaling, and JAK/STAT3 signaling to illustrate the underlying interplay mechanisms between m6A modification and ncRNAs in cancer stemness." (PMID 34345203, 2021). "Complete and systemic blockade of STAT3 signaling in the context of a normal immune system carries the risk of increased susceptibility to infections or cancer." (PMID 33411696, 2021). "Persistent and abnormal activation of STAT3 has always been linked to malignant cancer behaviors, including proliferation, metastasis, and invasion." (PMID 34059068, 2021). "In this study, we demonstrate that the natural mutations in the DNA-binding domain of STAT3 are associated with reduced malignancy of several cancers." (PMID 33535185, 2021). "The association between estrogen and STAT3 activation along with the association between STAT3 activity and mutant KrasG12D-induced cancer formation suggests a possible mechanism behind the phenotype of sex-dependent anal SCC development in KC mice." (PMID 34735515, 2021). "STAT3 overexpression is associated with the progression of various cancers, including LC, making it a potential target for cancer therapy." (PMID 33740988, 2021). "Based on published data, STAT3 activation has been linked to therapeutic resistance and cancer stemness." (PMID 34204116, 2021).
cancer (continued). "Increased IL‐6/JAK/STAT3 signalling is implicated in many human cancers and is associated with poor clinical prognosis." (PMID 33382511, 2021). "Signal transducer and activator of transcription 3 (STAT3), a cytokine transcription factor, has been linked with systemic inflammation in cancer cachexia." (PMID 34829914, 2021). "Janus kinase 2 (JAK2)/signal transducer and activator of transcription 3 (STAT3) signaling pathway is believed as a crucial link implicated in invasion, survival, growth and angiogenesis of cancer cells." (PMID 33976735, 2021). "IL-6 and IL-1 cause activation of STAT3, which can induce proliferation of cancer cells and migration via increased expression of matrix metalloproteinases." (PMID 34988471, 2021). "IL-6 is overexpressed in the TM and stimulates the JAK/STAT3 pathway, which is a molecular event that is associated with poor prognosis for cancer patients." (PMID 34440220, 2021). "In contrast, increased expression of STAT3 has been found in a variety of cancer cell lines and it is associated with poor disease prognosis and drug resistance." (PMID 33544704, 2021). "The IL-6/JAK/STAT3 pathway is also abnormally activated in many types of cancer, which is generally associated with a poor clinical prognosis." (PMID 35155571, 2021). "In this study, we found that PI3K/AKT/mTOR inhibitors upregulated MIF expression and secretion in several PTEN-deficient cancer cells, and activated STAT3 activity through JAK1, eventually limiting the effects of these inhibitors." (PMID 33431808, 2021). "In particular, curcumin has been reported to inhibit metastasis by blocking the activation of STAT3 (which is associated with cancer cell metastasis)." (PMID 34959384, 2021). "Collectively, we demonstrate that LIN28B enhanced STAT3 signaling causes inflammatory cytokines production and declines chemotherapeutic drugs sensitivity while increasing cancer stem cell markers, ALDH activity." (PMID 34837926, 2021). "STAT3 has been consistently implicated in promoting cancer cell invasion and metastasis in many cancer types and was shown here to bind to its cognate elements in the WASF3 promoter." (PMID 34465361, 2021). "Increased IL-6 stimulation is common in various cell lines and tumors and is linked to cancer metastasis and cancer cell survival as a result of STAT3 phosphorylation." (PMID 34944867, 2021). "Induction of signaling pathways such as STAT3 or PI3K pathway via up-regulation of SRC signaling has been linked to cancer progression." (PMID 34399705, 2021). "Both STAT3 and NF-κB plays role in cancer development and progression, STAT3 also regulates the expression of various cancer-causing genes in response to cancer-inducing stimuli." (PMID 35069196, 2021). "The main known effect of CT inhibiting cancer cell growth is linked to its capability of inhibiting STAT3 proteins." (PMID 33544704, 2021). "Activated STAT3 dimer induces the expression of multiple genes associated with anti-apoptosis, proliferation, angiogenic, and metastatic properties in cancer cells." (PMID 34887764, 2021). "Activation of STAT3 in malignant tumors has been implicated in poor prognosis, metastasis, and proliferation of cancers, and several STAT3 inhibitors are currently under development." (PMID 34679602, 2021). "The main mediator of muscle wasting in cancer cachexia is STAT3, together with a range of conditions associated with high activity of the IL-6-family signaling." (PMID 33557173, 2021). "The association between IL‐6 and JAK2, and STAT3 signalling pathway activation and cancer cell migration was observed in a paracrine or autocrine IL‐6‐rich inflammatory environment." (PMID 33759378, 2021). "Persistent STAT3 activity is associated with cancer progression, most of which show aberration of JAKs, Src, or other receptor tyrosine kinases." (PMID 33494352, 2021).
cancer (continued). "Our and other findings indicated that the specific role and underlying molecular mechanism of the lncRNA-H19/miR-29b-3p/STAT3 pathway in the initiation and development of cancer should be further explored in the future." (PMID 34475985, 2021). "The IL6/JAK/STAT3 pathway plays an important role in the signal transduction processes, which are associated with cell proliferation and the invasive phenotype of cancers." (PMID 35008199, 2021). "The IL-6/JAK/STAT3 pathway is aberrantly hyperactivated in many types of cancer, and such hyperactivation is generally associated with a poor clinical prognosis." (PMID 33540700, 2021). "Since SPATS2 has been implicated in cancer-related processes, to further explore the underlying mechanism, we focused on STAT3 and its downstream pathways." (PMID 33391405, 2021). "The enhanced activities on cancer cell growth by pulvomycin were partly associated with the inhibition of STAT3 activation." (PMID 33920736, 2021). "Our results revealed that the expression of STAT3/CDK2/4/6 was altered in various cancers and is associated with poor overall and disease-free survival of the cohorts." (PMID 33668805, 2021). "On the other hand, the structurally similar CypB, which was found in the endoplasmic reticulum, has been implicated in STAT3 activation and the generation of reactive oxygen species in cancer cells." (PMID 34187415, 2021). "Recently, a clinical study indicated that constitutive STAT3 activation caused the expression of Mcl-1 and Bcl-xL, resulted in cancer cell progression and survival." (PMID 34488773, 2021). "The siRNA-loaded NPs significantly inhibited the IL-6/STAT3 expression, which was associated with blockade of proliferation, colony formation, migration, and angiogenesis in the cancer cells." (PMID 34502560, 2021). "MiR-196b-5p plays a central role in maintaining CSCs characteristics associated with resistance to cancer therapy by targeting STAT3 signaling pathway in colorectal cancer stem cells." (PMID 34722553, 2021). "One such signaling cascade is the IL6 induction of JAK/STAT3 signaling, which has been described to influence cell growth and differentiation, and is, therefore, often implicated in cancer when dysregulated." (PMID 33763387, 2021). "Taken together, the feedback activation of the STAT3 signaling pathway in PTEN-deficient cancer cells limits the therapeutic efficiency of PI3K/mTOR inhibitors, which can be circumvented by targeting the PI3K and STAT3 pathways simultaneously." (PMID 33431808, 2021). "EGF is upregulated in IPF, COP, and fibrotic NSIP, and is linked to STAT3 activation in cancer progression." (PMID 34207510, 2021). "IL‐6 acts directly on cancer cells to trigger the expression of STAT3 target genes, the encoded proteins of which then drive cancer cell proliferation and survival, promoting angiogenesis, invasiveness, metastasis, and immunosuppression." (PMID 34131122, 2021). "In the TME, cancer-associated fibroblasts (CAFs) can promote and maintain the stem cell-like properties of liver cancer cells through the IL-6/STAT3/Notch signaling pathway." (PMID 34447750, 2021). "LLL12B inhibited STAT3 phosphorylation and down-regulated downstream target genes which are associated with cancer cell proliferation and growth." (PMID 33909625, 2021). "S1P induces inflammatory signaling via activating NF-κB and IL-6/STAT3 pathways intracellularly, which prevents apoptosis and enhances cell proliferation and angiogenesis colitis-associated cancer and chronic intestinal inflammation." (PMID 33920887, 2021). "The STAT3 alterations occur in 27 cancer types, comprising of mutation (136 cases, 61.81%), amplification (48 cases, 21.81%), deep deletion (25 cases, 11.36%), fusion (seven cases, 3.18%), and multiple alterations (four cases, 1.81%) occurred the least." (PMID 33668805, 2021). "The IL6/JAK/STAT3 pathway is hyperactivated in various types of cancer and is commonly associated with poor clinical prognosis." (PMID 35008199, 2021).
cancer (continued). "Deregulated STAT3 activation has been reported in various human cancers including HCC and linked with the advancement of cancer, chemoresistance, poor clinical outcome, and decreased overall survival rate." (PMID 35053027, 2021). "Feedback activation of STAT3 in oncogene-addicted cancer cells has been implicated in promoting drug resistance and can be inhibited to restore drug sensitivity." (PMID 34944848, 2021). "It has been shown in previous studies that the IL-6/JAK STAT3 pathway is abnormally highly activated in many cancers, which is generally associated with poor clinical prognosis." (PMID 33912584, 2021). "In this study, LLL12B inhibited STAT3 phosphorylation (tyrosine 705) and the expression of its downstream targets, which are associated with cancer cell proliferation and survival." (PMID 33909625, 2021). "Specifically, STAT3 overactivity has been associated with the invasion and proliferation of a significant variety of cancer cells both in vitro and in vivo, and as such has been recognized to be a strong oncogene." (PMID 34395259, 2021). "A deeper analysis identified the downregulation of GM-CSF/M-CSF, IL-6, and TNF-α and the inhibition of the NF-κB/IL-6/STAT3 pathway as further contributors to colitis-associated cancer." (PMID 34950252, 2021). "STAT3 has been noted to play a role in many types of cancer and has been associated with a worse prognosis in specific cancers." (PMID 34680318, 2021). "Cancer promotion can be regulated by several pathways associated with inflammation, such as those involving NF-κB, STAT3, mTOR, and MAPKs, which are triggered by pro-inflammatory cytokines like IL-6, TNF-α, and IL-1β." (PMID 34950252, 2021). "A preliminary analysis showed that one of the cancer cell lines with all correctly targeted alleles had a high expression of active (i.e., tyrosine phosphorylated) STAT3." (PMID 34675248, 2021). "In contract, STAT3 transforms to hyper- and sustaining-activated in cancer for the excessive cytokine supply and ultra-active mutation within kinase pathway, which promotes cancer metastasis, angiogenesis, and immuno-suppression." (PMID 34502195, 2021). "We used the TCGA database to investigate the mutation status in the coding region of STAT3 among 10953 cases from 32 types of cancers and identified 1.3% mutation (121 mis-sense and 22 truncating mutations)." (PMID 33535185, 2021). "We examined several proteins that can regulate muscle growth and are implicated in cancer cachexia, including STAT3, p38 MAPK, and ERK1/2." (PMID 34395422, 2021). "Various tools and resources have been applied for in-depth studies on the mechanisms underlying carcinoma progression, and STAT3 activity has emerged as an important mechanism for regulating carcinogenesis and metastasis." (PMID 34513827, 2021). "A number of reports have revealed that the cytokine-induced activation of STAT3 is associated with the evasion of apoptosis, among other cancer hallmarks." (PMID 31936675, 2020). "Increased sensitivity to chemotherapy in T2-KD cancer cells was associated with an inability to activate the STAT3 pathway and a consequent deficit in chemotherapy resistance and CSC traits." (PMID 33023532, 2020). "As discussed, the transcription factor STAT3 is associated with tumourigenesis in several types of cancers." (PMID 32731620, 2020). "The inhibition of the STAT3-FAK-SRC axis is implicated in lowering the cancer stem cell load, tumorigenic potential, and metastasis." (PMID 33240810, 2020). "STAT3 and the accompanying signalling pathways have been associated with multiple mechanisms of resistance to cancer therapies." (PMID 32731620, 2020). "IL-6 and TLRs activate STAT3, a key transcription factor that regulates genes implicated in cell proliferation, cell cycle progression, cell survival, and angiogenesis in cancer." (PMID 33180876, 2020). "Loss of STAT3 enhances T-cell recruitment and activation and a STAT3-dependent chronic inflammation is required for the cancer immune evasion." (PMID 32483429, 2020).